XBP1 (X-box binding protein 1)
Diseases named in the same sentence as XBP1 in open-access papers (continued):
Sharing a sentence is not in itself a finding about the gene and the disease.
breast carcinoma (continued). "Both XBP1-u and XBP1-s are highly expressed and can drive the development of a variety of tumors, including colorectal cancer, hepatocellular carcinoma, multiple myeloma, ovarian cancer, breast cancer, melanoma, and bladder cancer, by regulating various aspects of tumorigenesis." (PMID 35269888, 2022). "Similarly, XBP1 expression appeared to be maintained by high transcriptional activity, which promotes triple‐negative breast cancer and is a candidate therapeutic target in high Myc‐expressing breast cancer." (PMID 34730297, 2021). "Moreover, several studies linked estrogen receptor signaling to the regulation of the UPR: the glucose regulated protein 78 (GRP78), also called binding immunoglobulin protein (BiP), and the x-box binding protein 1 (XBP1) are upregulated in endocrine- and chemotherapy-resistant breast cancers." (PMID 30781465, 2019). "ERβ1 might target IRE1/XBP-1 pathway to promote the apoptosis of breast cancer cells." (PMID 31065692, 2019). "Additionally, in breast cancer cell lines, overexpression of XBP1 promotes EMT67." (PMID 28332555, 2017). "Thus, to determine whether WA induced ROS has any role in the induction of UPR in breast cancer cells;cellular RNA was extracted and used for RT-PCR to monitor splicing of XBP-1 mRNA." (PMID 28033383, 2016). "Finally, we investigate XBP1s expression in over 170 breast cancer patients' samples, and show that XBP1s expression is highly correlated with overall survival in ER+ breast cancer patients, strongly suggesting a potential therapeutic application of XBP1 inhibitors in breast cancer treatment." (PMID 26517687, 2015). "XBP1 regulates a subset of ER-resident chaperone genes that are essential for protein folding and maturation; and its upregulation has been reported in various human solid tumors including breast cancer, hepatocellular carcinoma, pancreatic adenocarcinomas and colon cancer patients." (PMID 27668268, 2015). "This study indicates that XBP1 is prominently and specifically expressed in HR+/HER2− breast cancer, and correlated with unfavorable response and poor progression‐free survival in patients with MBC receiving the combined therapy." (PMID 40940685, 2025). "Western blot assay also indicated a slightly elevated trend of XBP1 and XBP1s expression in HR+/HER2− breast cancer cell lines." (PMID 40940685, 2025). "Although direct evidence implicating ATF6 in breast cancer progression is limited, indirect regulation of GRP78 and spliced XBP1 (XBP1s) has been reported in hepatocellular carcinoma, suggesting a potential mechanistic crosstalk among the UPR branches." (PMID 40564269, 2025). "Two positive targets, XBP1 and NAGLU, were obtained based on the eQTLGen in the analysis of AF and breast cancer (total)." (PMID 39170695, 2024). "For the non-cancer adipose-breast network that we applied to the breast cancer GWAS, Downstreamer prioritised seven known breast cancer driver genes among the top 100 genes: CREBBP, TRPS1, ARID1A, ARID1B, XBP1, SPEN and NUMA1." (PMID 39010058, 2024). "Increased expression of XBP1-SMRNA and protein was observed in endocrine-resistant breast cancer cells, which promoted SERM and SERD resistance." (PMID 39544302, 2024). "In performing the analysis of AF with breast cancer (ER+), WNT3 and XBP1 were obtained based on eQTLGen." (PMID 39170695, 2024). "While the role of XBP1 in UPR is well-characterised, emerging evidence suggests its involvement in endocrine resistance in breast cancer." (PMID 38203358, 2023). "We observed an inverse relationship between the mRNA levels of XBP1 and PPARGC1B in the TCGA breast cancer dataset." (PMID 38203358, 2023). "We next determined the expression of RRM2, CDC6, and TOP2A mRNA and protein in XBP1-knockout sub-clones of MCF7 cells and ER-positive (MCF7, T47D, and BT474) breast cancer cells after treatment with STF083010." (PMID 36997866, 2023).
breast carcinoma (continued). "In breast cancer, MYC was shown to directly regulate the transcription of ERN1 by binding to its promoter and enhancer and to cooperate with XBP1, leading to enhanced transcriptional activity." (PMID 35349489, 2022). "In breast cancer cells, UPR stimulation and estrogen can enhance the level of XBP1-s, which in turn promotes tumor cell proliferation by activating the transcription of NCOA3 as well as the Rab9/PIK/Akt pathway." (PMID 35269888, 2022). "In breast cancer tissues, IRE1 expression correlated positively with CCDC170 and X-box binding protein 1 expression at both the mRNA and protein levels." (PMID 33291081, 2020). "In some cases, UPR induction is clearly linked with a malignant phenotype and aggressiveness, as shown by XBP1 overexpression in human multiple myeloma, and overactivation of PERK-ATF4 in MYC-induced lymphomas, breast cancers and colorectal adenocarcinomas." (PMID 31071975, 2019). "Particularly, the human X-box binding protein-1 (XBP1), a key transcription factor, plays a critical role in breast cancer drug resistance through regulating alternative splicing in UPR stress signaling pathway." (PMID 31065692, 2019). "In human breast carcinomas, high GRP78 and XBP1 protein levels are found in comparison with normal tissue." (PMID 31064137, 2019). "Basic research has provided compelling evidence is support of targeting IRE1/XBP1, PERK, and GRP78 to improve treatment outcome for breast cancer in the clinic." (PMID 30248920, 2018). "Many in vivo and in vitro studies directly implicate XBP1 in the pathology of TNBC and luminal breast cancers." (PMID 30248920, 2018). "From the perspective of the mechanisms, our findings demonstrated that XBP1 and HIF-1α are upstream driver genes of MALAT1 in TNBC cells, while Her-2 is an upstream driver gene of MALAT1 in Her-2 positive breast cancer cells." (PMID 29416769, 2018). "In support of this finding, patient-derived BCM-2147 (TNBC), MDA-MB-231 (TNBC), NeuT EMTCL2 (mouse breast cancer cell line), and transformed MCF10A cells transplanted into mice form significantly fewer tumours when XBP1 was silenced." (PMID 30248920, 2018). "Recent studies have shown that STF-083010, an inhibitor for XBP1, can restore sensitivity to tamoxifen in tamoxifen resistant MCF-7 cell lines and a synergistic effect of both drugs significantly delay breast cancer progression." (PMID 30159133, 2018). "Among samples with TNBC, XBP1 and HIF-1α exhibited much higher expressions in samples with highly metastatic breast cancer than those with poor metastasis." (PMID 29416769, 2018). "Of the four biomarkers we detected, ESR1 is the only one in common with the reported signature for luminal breast cancers (ESR1, GATA3, FOXA1, XBP1, and cMYB)." (PMID 29868123, 2018). "XBP1 and ESR1 are co-expressed in luminal breast cancers and in vitro work has demonstrated the existence of a feed-forward mechanism connecting the two proteins." (PMID 30248920, 2018). "Among the top 10 genes selected by dwgLASSO, UBE2S, SALL2, XBP1 and KIAA0922 have been previously reported to be relevant in breast cancer biomarker discovery study." (PMID 28187708, 2017). "XBP1 is activated in TNBC and has a pivotal role in the tumorigenicity and progression of this human breast cancer subtype by controlling HIF1α pathway." (PMID 28245581, 2017). "The general trend of the three HER2/neu-positive breast cancer cell lines tested was that they possessed higher basal levels of DDIT3/CHOP, ATF6 and spliced XBP1 and that these levels increased in response to palmitate treatment." (PMID 27464732, 2016). "Our study examines a new selective immunotherapeutic strategy by targeting XBP1 in different types of cancers including MM, SMM, breast cancer, colon cancer, and pancreatic cancer." (PMID 27668268, 2015).
breast carcinoma (continued). "As compared to the XBP1-CTL control, lenalidomide-treated XBP1-CTL (n=3) showed increased IFN-γ production in response to HLA-A2+ MDA-MB231 (breast cancer), Panc1 (pancreatic cancer) or SW480 (colon cancer) cells." (PMID 27668268, 2015). "Breast cancer tumors have elevated UPR signaling components, including GRP78 and XBP1, which drive endocrine therapy resistance." (PMID 26157705, 2015). "In the ten SUM breast cancer cell lines we investigated, three lines have both ERLIN2 gene amplification and up-regulation of activated XBP1, resulting in dramatically high-level expression of ERLIN2 protein." (PMID 22681620, 2012). "Previous work has demonstrated that breast cancer cells over express XBP1, while we observed that SUM-44, SUM-52 and SUM-225 cell lines over expressed total and activated XBP1." (PMID 22681620, 2012). "Most importantly, STAT1-/- mammary tumors express elevated levels of ERα, PR, GATA3, AREG, XBP1, and FOXA1, all of which are regulated by the transcriptional control of ERα." (PMID 22264274, 2012). "Of the ex-vivo breast cancer samples on the tissue micro array, 76% stained strongly (score >6/9) for GRP78 and 90% stained strongly for XBP1." (PMID 19861963, 2009). "This study is the largest series of breast cancer cases showing UPR activation as shown by upregulation of GRP78 and that a key downstream effector of the UPR, XBP1, is also over-expressed." (PMID 19861963, 2009). "As expected, this list contains numerous markers of breast cancer cells whose expression specificity was previously reported by other (notably ERBB3, XBP1, KRT18, IL6ST, CREB1, TFF1, TFF3)." (PMID 19104654, 2008). "Similarly, IRE1α–XBP1 signaling facilitates EMT by downregulating E-cadherin and upregulating N-cadherin in breast cancer and colorectal carcinoma cells." (PMID 41228282, 2025). "XBP1 can be used as a common druggable gene for AF and breast cancer, and there are no potential side effects of treatment against this target." (PMID 39170695, 2024). "In the present study, we aim to investigate the expression levels of NEAT1, LINC00299, and CASC2 genes in breast cancer samples compared to adjacent nonmalignant samples, as well as their relationship with the spliced XBP1 mRNA level." (PMID 37706018, 2023). "Interestingly, in contrast to Lyn and Lck, the activity of c-Src was essential for UPR activation (XBP1 and HSPA5 induction) in human breast cancer cell lines revealing differential involvement of SFKs in stress responses." (PMID 37680627, 2023). "A previous study on cancer intrinsic IRE1α-XBP1 signaling in breast cancer employed immunocompromised mice and therefore, did not evaluate the impact of XBP1 loss on the immune microenvironment." (PMID 36624093, 2023). "Importantly, in addition to the XBP‐1 axis of the endoplasmic reticulum UPR, our group has reported that in breast cancer cell lines, mitochondrial stress activates an ERα axis of the mitochondrial UPR (UPRmt)." (PMID 36111352, 2022). "Our data show that the expression of POLR3G in breast cancer samples was negatively correlated with that of eight out of ten genes (GATA3; XBP1; AGR2; SIDT1; AR; SPDEF; FOXA1; MLPH) in a list of signature genes most differentially expressed in luminal A compared to basal-like tumors." (PMID 36497214, 2022). "XBP1 is involved in chemoresistance and progression in TNBC, and XBP1 depletion impairs angiogenesis and promotes sensitivity to chemotherapy in HER2-positive breast cancer." (PMID 36148946, 2022). "In addition to well‐known markers for breast cancer (ER, PR, HER2), XBP1, which has been suggested to be upregulated in breast cancer tissues, is shown as a representative example of a significant change in TR." (PMID 34730297, 2021). "In addition to splicing of XBP1, IRE1 has also contributed to the degradation of a subset of tumor-suppressive miRNAs in breast cancer, suggesting unexpected roles of IRE1 in tumor initiation and progression." (PMID 33746610, 2021).
breast carcinoma (continued). "We showed that oestrogen increased co-recruitment of ERα and XBP1 to target genes and that knockdown of XBP1 blunted the oestrogen-mediated induction of oestrogen-responsive genes only in endometrial cancer cells and not breast cancer cells." (PMID 32069845, 2020). "Previous studies have demonstrated that XBP1 expression is correlated with NAT1 expression, and XBP1 and NAT1 may share a common transcriptional network in breast cancer." (PMID 32793479, 2020). "XBP1 motivates triple-negative breast cancer via affecting the HIF1 α pathway and promotes snail expression to induce epithelial-to-mesenchymal transition as well as invasion of breast cancer cells." (PMID 31534839, 2019). "Importantly, studies with tumor samples from patients with colorectal carcinoma, breast cancer and oral squamous cell carcinoma, described the overexpression of IRE1 or XBP1 in metastatic samples compared to the primary tumors." (PMID 31064137, 2019). "Here we demonstrate the application of a biochip to simultaneous detection of the two XBP1 isoforms in models of breast cancer, non-adherent cells and inflammation." (PMID 31807121, 2019). "Additional work is required to establish if XBP1 activates c-MYC expression in breast cancer cells as well, and whether c-MYC regulates IRE1 expression and XBP1 activity in PCa cells." (PMID 30679434, 2019). "Previous studies have shown that breast cancer cell lines lacking XBP1 exhibit attenuated tumorigenesis due to impaired assembly of XBP1/HIF-1 transcriptional complex and substantial inhibition of downstream hypoxia-responsive genes expression." (PMID 30250843, 2018). "This notion is corroborated in cell lines where basal-like cells are found to display higher levels of XBP1 splicing compared to luminal breast cancer and non-transformed cells." (PMID 30248920, 2018). "For the UBC-TAM Series univariate analysis, favorable prognostic associations for breast-cancer-specific survival (BCSS) were detected for non-silent mutations in MAP3K1, ERBB3, XBP1, and PIK3CA." (PMID 30181556, 2018). "Significant changes in the level of CHOP and splicing of XBP1 were only found in breast cancer cells, and not found in normal MCF-10A cells." (PMID 28441457, 2017). "Importantly, short-term lenalidomide exposure further increased the proportion of CD45RO+CCR7+ central memory CD3+CD8+ T cell subset within the XBP1-CTL, leading to enhanced anti-tumor activities against breast cancer, colon cancer and pancreatic cancer cells." (PMID 27668268, 2015). "In our previous studies, XBP1-CTL induced using the HLA-A2-specific XBP1 US184-192 (YISPWILAV) and XBP1 SP367-375 (YLFPQLISV) peptides displayed HLA-A2-restricted and antigen-specific activities against breast cancer, colon cancer and pancreatic cancer cells." (PMID 27668268, 2015). "In addition, the frequency of Eomes+ IFN-γ+/CD3+ CD8+ T cells was increased in response to breast cancer (MDA-MB231), pancreatic cancer (Panc1) or colon cancer (SW480) cells in the lenalidomide treated XBP1-CTL." (PMID 27668268, 2015). "XBP1s expression level may be one of the key players in tamoxifen-resistant breast cancer, while IRE1, the upstream nuclease which mediates the splicing of XBP1 pre-mRNA, may be a potential target for reducing resistance." (PMID 26517687, 2015). "In particular in the XBP1s reporter mouse model, which develops spontaneous mammary tumors, XBP1 splicing was found to increase upon exposure to a nonmetabolizable glucose analog that simulates glucose deprivation." (PMID 26491226, 2015). "Our findings show that GRP78, IRE1α, phospho-JNK and XBP1(s) are robustly upregulated in antiestrogen resistant ER + breast cancer cells in the presence of glutamine but absence of glucose." (PMID 25339305, 2014). "Importantly, the study confirms XBP-1(S) as an essential regulator of BCL2 transcription, which is a prosurvival/antiapoptotic factor and confers resistance to aromatase therapy in breast cancer patients." (PMID 23192763, 2013).
breast carcinoma (continued). "Forced expression of IRE1α, or spliced XBP1, the target of IRE1α under ER stress, up-regulated expression of the ERLIN2 protein, while knockdown of IRE1α RNase activity decreased ERLIN2 expression in the ERLIN2-amplified breast cancer cells." (PMID 22681620, 2012). "We performed Phenome-wide MR Analysis of XBP1 with 783 non-AF, non-breast cancer phenotypes." (PMID 39170695, 2024). "Notably, investigations of the role of IRE1 in breast cancer have focused exclusively on XBP1 and no data regarding roles for RIDD or IRE1 kinase activity have been reported." (PMID 30248920, 2018). "The ERS-associated transcription factor XBP-1 is known to be specifically activated in TNBC and not in other subtypes of breast cancers, but the degree of expression of other UPR regulators in each subtype is unknown." (PMID 27494867, 2016). "Similarly, XBP1 has been shown to upregulate methyltransferase-like 3 (METTL3) and METTL4 to enrich m6a methylation and thus promote the mRNA stability of Calcium Binding And Coiled-Coil Domain 1 (CALCOCO1) and p62 (known ER-phagy regulators) in breast cancers." (PMID 41301006, 2025). "Importantly, XBP1 pathway activation correlates with poor patient survival in TNBC, suggesting that its specific inhibition may enhance anti-tumor therapies and representing as alternative treatment strategies for this aggressive breast cancer subtype." (PMID 27668268, 2015). "The FOXA1 gene, which opposes SOX10 expression, cooperates with ER1 to maintain luminal identity in breast cancer, whereas GATA3, XBP1, and CA12 showing a negative correlation with SOX10, also cooperate in ER1 signaling." (PMID 36496864, 2022). "In a seminal paper, Laurie Glimcher’s group identified an XBP1 gene signature using ChIP-Seq which correlated with shorter relapse free survival in two cohorts of TNBC patients, but not in ESR+ breast cancer patients." (PMID 30248920, 2018). "To further confirm that T3-induced XBP-1 alternative splicing was independent of the presence of ERβ, we repeated the experiment on a specific clone of MCF-7 breast cancer cells not expressing ERβ." (PMID 28031751, 2016). "Lenalidomide induced Akt upregulation was seen in both central memory and effector memory XBP1-CTL subsets, but not the terminal effector subset, in response to breast cancer (MDA-MB231) and colon cancer (SW480) cells." (PMID 27668268, 2015). "For example, why does the co-occupancy of XBP1 and HIF-1α occur in TNBC but not luminal breast cancer cells?" (PMID 25927911, 2014). "Given the fact that the ER stress inducer PERK was more expressed in breast cancer cells lacking STARD7, we also look at levels of other ER stress downstream targets such as Eukaryotic Initiation Factor 2α (EIF2α), X box‐binding protein 1 (XBP1) and Activating transcription factor 4 (ATF4)." (PMID 40443279, 2025).